FTO (FTO alpha-ketoglutarate dependent dioxygenase)
Diseases named in the same sentence as FTO in open-access papers (continued):
Sharing a sentence is not in itself a finding about the gene and the disease.
Obesity (continued). "Our RNA sequencing data showed that CKMT1A and B, futile cycle maintaining creatine kinases, were expressed higher in DN as compared to SC adipocytes and less abundant in those that had an obesity-risk genotype of the rs1421085 FTO locus." (PMID 32316277, 2020). "It is widely known that the FTO gene is an established genetic susceptibility locus for the risk of obesity development." (PMID 33114268, 2020). "Linear and logistic regression analyses with adjustment for age and gender were employed to investigate the association between FTO genotypes, haplotypes and obesity parameters." (PMID 31915589, 2020). "Some genes such as the fat mass and obesity-associated (FTO) gene are strongly associated with obesity and overweight." (PMID 31996075, 2020). "There are several pathways suggested for the exact underlying mechanism of the effect of FTO on obesity." (PMID 32398148, 2020). "In conclusion, the FTO polymorphisms showed astrong association with development of extreme phenotype of obesity andadiposity modulation in a Brazilian population." (PMID 32154826, 2020). "This means that the association of the FTO risk alleles with obesity measures is weaker in physically active subjects than in physically inactive subjects." (PMID 32457790, 2020). "Previous studies also show that PA attenuates the excess risk of obesity conferred by risk variants of FTO." (PMID 32835373, 2020). "Genotyping was performed by real time PCR.Our results showed a strong association between FTO variantsand extreme obesity." (PMID 32154826, 2020). "The fat mass and obesity associated (FTO) gene is located on the chromosome region 16q12.2 and was reported to be strongly associated with obesity." (PMID 32843047, 2020). "In 2007, genome-wide association study identified the fat mass and obesity-associated (FTO) gene as an obesity susceptibility gene." (PMID 32050935, 2020). "Here, it is reported that peripheral nerve injury increases the expression of the m6A demethylase fat‐mass and obesity‐associated proteins (FTO) in the injured DRG via the activation of Runx1, a transcription factor that binds to the Fto gene promoter." (PMID 32670741, 2020). "Given the connection with obesity, many studies have been conducted to identify the association between genetic variants in FTO and risk of T2D/GDM." (PMID 32390949, 2020). "We aimed to assess anthropometric indices in carriers of FTO rs9939609 polymorphism with overweight across Iranian population (Shiraz) to find out the associations of this polymorphism with obesity indices." (PMID 32398148, 2020). "Another set of polymorphisms associated with age related diseases is at FTO (fat mass and obesity associated) gene, which are involved in increased morbidity and mortality due to increased adiposity and obesity in humans." (PMID 33262758, 2020). "The FTO locus manifests the strongest association signal with obesity in both Asian and European populations." (PMID 33193685, 2020). "Interactome network analysis of the lower expressed genes in FTO obesity-risk genotype suggests that under normal conditions, DECR1 (dienoyl-CoA reductase), LIPE, LDHB, SOD2, ATP5B, and J are central elements in maintaining connectivity." (PMID 32316277, 2020). "As a next step, we investigated all the DEGs based on the presence of the FTO obesity-risk allele in the white- and brown-differentiated DN and SC samples, and 1295 DEGs were identified." (PMID 32316277, 2020). "Altogether, four SNPs (rs1121980, rs1558902, rs9939609, and rs9941349) located in the fat mass and obesity-associated (FTO) gene showed significant association with WC (as a continuous outcome) in both populations." (PMID 32384785, 2020). "FTO, an m6A demethylase that regulates transcriptomic m6A modifications in mRNA88, is associated with metabolic disorders such as diabetes and obesity, diseases in which the heart is vulnerable to I/R injury." (PMID 32581252, 2020).
Obesity (continued). "Association studies of the FTO gene with obesity or obesity-related traits have been reported in many populations across the world, confirming the strong association of FTO SNPs with BMI and/or obesity." (PMID 31915589, 2020). "The obesity-associated FTO SNPs in East Asian populations are comparable to that of people of European descent." (PMID 33304380, 2020). "Some researchers have reported that FTO gene influences PCOS mainly via the association with obesity or obesity-related parameters such as BMI." (PMID 32050935, 2020). "We next explored the potential association of both adherence to the Mediterranean diet and percentage of overweight-obesity with the well-known obesity risk allele A of the rs9939609 SNP in the FTO gene." (PMID 32398726, 2020). "Mammals have nine different ALKBH family members: ALKBH1 to ALKBH8 and the fat mass and obesity-associated (FTO) protein." (PMID 32933187, 2020). "In Indonesian population, most report on FTO rs9939609 SNP association with obesity came from the western part of the country, namely North Sumatera, Yogyakarta, West Sumatera (Susmiati, Surono & Jamsari, 2018), and DKI Jakarta." (PMID 31915589, 2020). "FTO was first found to be linked to obesity in multiple human populations and ethnic groups in population studies." (PMID 33162550, 2020). "The aim of this study was to evaluate the association between FTO single nucleotide polymorphisms (SNPs), daily macronutrient intake, and obesity and its metabolic consequences." (PMID 33114268, 2020). "Fat mass and obesity-associated protein (FTO), which was first found to be linked to obesity in population studies, partially colocalizes with nuclear speckles and exhibits efficient oxidative demethylation of abundant m6A in RNA40,41." (PMID 33162550, 2020). "The FTO SNPs within intron one are the most penetrant common polymorphisms related to obesity in Europeans." (PMID 33348678, 2020). "In conclusion, our findings provide new insights into the role of the interactions between diet and FTO SNPs in the risk of obesity and its metabolic consequences." (PMID 33114268, 2020). "The common single nucleotide polymorphisms (SNPs) rs9939609 and rs1421085 of the fat mass and obesity-associated (FTO) gene have been repeatedly reported as one of the important obesity genetic risk factors." (PMID 31915589, 2020). "The aim of our study was to evaluate the role of the FTO rs9939609and rs17817449 polymorphisms in the risk of extreme obesity, period of obesityonset, and in relation to anthropometric and biochemical parameters." (PMID 32154826, 2020). "The comprehensive series of GWASs presented here validates associations of obesity and BMI found in previous studies, such as the FTO and NEGR1 loci." (PMID 31888951, 2020). "FTO single-nucleotide polymorphisms, which are mostly located in intron-1, were found to be linked with obesity in humans." (PMID 33511112, 2020). "Some candidate genes have been robustly reported to be associated with complex traits, such as the fat mass and obesity-associated (FTO) gene on body mass index (BMI), and the fibroblast growth factor 5 (FGF5) gene on blood pressure levels." (PMID 32457790, 2020). "In this study, we showed that having the FTO rs9939609 and rs1421085 SNPs risk alleles increase the risk for obesity." (PMID 31915589, 2020). "We hope that further work extends our preliminary findings to determine if chronic repetitive stimuli (i.e. exercise training), lowers the obesity risk in individuals with the FTO risk variant by modulating FTO protein and/or function." (PMID 32821265, 2020). "The obesity-associated SNPs in the first intron of FTO are functionally connected with the IRX3 gene." (PMID 32651404, 2020). "FTO was first recorded as an obesity susceptibility gene and was later reported as a T2D associated body mass index (BMI) gene." (PMID 33113859, 2020).
Obesity (continued). "In terms of the potential mechanisms between mutations in FTO and increased risks of obesity, studies have proven the role of FTO in the influence of food intake." (PMID 33304380, 2020). "Human obesity is linked to mutations within the FTO gene, which controls the expression of neighboring genes." (PMID 32299393, 2020). "By conducting GWAS analysis, researchers have found that FTO SNPs are associated with obesity and higher risks of various cancers in multiracial populations." (PMID 33304380, 2020). "In this study, we examined the association of FTO rs9939609 and rs1421085 with obesity in Balinese of the Bali Province, Indonesia." (PMID 31915589, 2020). "LADA has also been linked to genes associated with type 2 diabetes, for example, risk variants of the transcription factor 7-like 2 (TCF7L2) gene and in one study, with the fat mass and obesity-associated (FTO) gene." (PMID 32835373, 2020). "Another super-enhancer, which is located on an obesity-risk associated locus of the intronic region of the FTO gene, was linked to the regulation of browning in subcutaneous fat by determining the level of IRX3 and IRX5." (PMID 32316277, 2020). "The fat mass and obesity-associated (FTO) rs9939609 gene variant has the highest minor allele frequency compared to other FTO variants." (PMID 32028392, 2020). "We identified that FTO rs9939609 and rs17817449polymorphisms have a strong association with extreme obesity and adipositymodulation in a Brazilian population sample." (PMID 32154826, 2020). "Fat mass and the obesity-associated protein (FTO) gene (p = 4.4 × 10−17), one of the most extensively studied genes in the field of food consumption and obesity, was associated with DC2 at the gene analysis further supporting previous candidate gene studies." (PMID 32066663, 2020). "FTO rs9939609 and rs17817449 were reported to be related to metabolic syndrome, type 2 diabetes mellitus, and obesity; rs8050136 and rs7195539 were associated with type 2 diabetes mellitus in a Uyghur population." (PMID 33817272, 2020). "These associations are consistent with prior studies demonstrating that higher numbers of FTO obesity-related risk alleles were associated with more eating episodes per day, higher calories consumed at lunch, and stronger responses to food cues." (PMID 32692747, 2020). "The FTO gene is the first obesity susceptibility gene to be identified by two GWAS in European populations." (PMID 32397403, 2020). "Previous work has reported higher fasting and postprandial glucose and insulin concentrations in carriers of obesity-risk FTO allele, yet this is eradicated when adjusted for BMI." (PMID 33348678, 2020). "Genome-wide association studies (GWAS) have shown that single nucleotide polymorphisms (SNPs) in intron 1 of the FTO (Fat mass and obesity associated) gene are strongly correlated with an increased risk of obesity in humans." (PMID 32747736, 2020). "Mutations in the FTO gene raise blood levels of leptin, a known mediator or growth factor between obesity and colon cancer, which activates a variety of pathways associated with colon cancer." (PMID 33304380, 2020). "FTO was the first identified gene contributing to human obesity, and its polymorphisms are closely related to insulin resistance and metabolic diseases." (PMID 32733807, 2020). "FTO is the first obesity-susceptibility gene identified in genome-wide association studies, and it was identified in many different human groups." (PMID 33262703, 2020). "The FTO allele associated with obesity represses mitochondrial thermogenesis in adipocyte precursor cells in a tissue-autonomous manner." (PMID 33262703, 2020). "The hASCs were isolated from paired DN and SC adipose tissue samples of nine donors, three of each FTO rs1421085 genotype: T/T-risk-free, T/C-heterozygous, and C/C-obesity-risk." (PMID 32316277, 2020). "In the previous studies, FTO was identified to be related to increased risk of obesity and a T2D incurrence." (PMID 32193455, 2020).
Obesity (continued). "Some polymorphisms in the FTO gene have been found to be associated with obesity, higher energy intake, and decreasing sleep duration." (PMID 32111069, 2020). "Although the specific mechanisms for FTO polymorphism and high risk of obesity and cancer are elusive, the correlation is definite." (PMID 33304380, 2020). "The ProFAT and BATLAS data clearly suggest that hASCs, which carry the FTO C/C obesity-risk genotype, have significantly lower browning potential." (PMID 32316277, 2020). "A meta-analysis study has found that 25 FTO SNPs including the rs9939609 and the rs1421085, were specifically associated with obesity in females only." (PMID 31915589, 2020). "Sequence variants in the first intron of FTO are strongly associated with human obesity, and carriers of the risk alleles show evidence of increased appetite and food intake." (PMID 32651404, 2020). "A study in an Asian Indian population has shown that lifestyle factors can influence the association of FTO gene with obesity traits." (PMID 32397403, 2020). "The variant FTO rs9939609 is the most extensively studied, located within the first FTO intron which has two alleles, A and T, the former linked to an increased risk for both obesity and type 2 diabetes mellitus." (PMID 32050935, 2020). "This studyevaluated the contribution of FTO polymorphisms (rs9939609 andrs17817449) for extreme obesity in terms of the period of obesity onset,anthropometric, and biochemical parameters." (PMID 32154826, 2020). "Another intriguing example of functional enhancer variation has been reported for the obesity-associated gene FTO (fat mass and obesity-associated protein)." (PMID 32486876, 2020). "Insufficient FTO gene or partial loss of FTO gene expression is related to a reduction of obesity, inversely, overexpression of FTO leads to obesity and weight gain in mice." (PMID 33330653, 2020). "Genome-wide association studies in the FTO gene have identified SNPs correlating with obesity and type 2 diabetes." (PMID 32747736, 2020). "FTO is known to be associated with body mass and obesity in humans and its over-expression affects the energy metabolism of cancer cells." (PMID 32299393, 2020). "In our study, IRX3 was significantly higher expressed in samples with FTO obesity-risk alleles and support its suppressive role in thermogenesis." (PMID 32316277, 2020). "Genome-wide association studies (GWAS) have uncovered multiple common variants associated with BMI and obesity with low to modest effect size, the most notable being the fat mass and obesity-associated (FTO) gene." (PMID 32630256, 2020). "The fat mass and obesity-associated gene (FTO) rs9939609 A-allele is linked to obesity and dyslipidemia, yet the independent influence of this polymorphism on blood lipids remains equivocal." (PMID 33348678, 2020). "Experiments have shown that T>C base changes in rs1421085, an intronic variant of the FTO gene found in GWASs on obesity, is involved in the regulation of adipocyte thermogenesis by increasing the expressions of nearby IRX3 and IRX5, but not FTO." (PMID 32271837, 2020). "The risk allele A of FTO SNP rs9939609 was closely related to obesity and BMI in Chinese, ethnic Chinese, Malaysian, Singaporean, East, and South Asian people." (PMID 33304380, 2020). "Pathway analysis of genes with different expression based on tissue origin and presence of the FTO obesity-risk allele revealed that different pathways dominated the two." (PMID 32316277, 2020). "Evaluation by BATLAS further highlighted FTO obesity-risk allele dependent differences, as 23 out of these genes were significantly lower expressed in samples carrying the FTO C/C obesity-risk allele (red rectangle)." (PMID 32316277, 2020). "The fat mass and obesity-associated protein (FTO) is known to be associated with body mass and obesity in humans and its over-expression affects the energy metabolism of cancer cells." (PMID 32299393, 2020).
Obesity (continued). "Human adipose-derived stromal cells were obtained from subcutaneous neck (SC) and DN fat of nine donors, of which 3-3 carried risk-free (T/T), heterozygous or obesity-risk (C/C) FTO genotypes." (PMID 32316277, 2020). "This article provided insights into how FTO predisposes to stimulated energy intake and obesity in humans." (PMID 33304380, 2020). "Among obesity-associated genetic factors, the fat mass and obesity-associated (FTO) gene on chromosome 16 has been recognized as one of the most studied genes to date." (PMID 32398148, 2020). "The possible relationship between FTO expression, overweight/obesity, and the risk of various types of cancers including hematopoietic malignancies such as myeloma, lymphoma, and leukemia is interesting." (PMID 32916783, 2020). "For example, physical activity has been found to attenuate the influence of the fat mass and obesity-associated (FTO) gene on obesity risk." (PMID 32457790, 2020). "Several genetic studies demonstrated an association between FTO (“fat mass and obesity-associated”) gene variants and obesity." (PMID 32098227, 2020). "One of the lead genomic signals associated with obesity in humans corresponds to intronic variants within the FTO locus, and follow-up studies have suggested this gene is implicated in the control of body mass." (PMID 32603637, 2020). "The FTO locus has been strongly associated with BMI, obesity, and, subsequently, type 2 diabetes as a clinical end point." (PMID 31998841, 2020). "As a result, the gene was named as the fat mass and obesity-associated (FTO) gene and has received extensive attention." (PMID 33304380, 2020). "We have examined the associations of FTO rs9939609 and rs1421085 SNPs with obesity in the 612 unrelated Balinese subjects living in urban and rural areas." (PMID 31915589, 2020). "Over the last decade, the study of dietary patterns and their relation to genetic risk of obesity has received more attention; nevertheless, the associations between FTO single nucleotide polymorphisms and dietary patterns need further investigation." (PMID 33114268, 2020). "Albeit, obesity is concomitant to various inherited and behavioral determinants that further predisposes to other chronic diseases; the FTO is also incriminated in adipogenesis." (PMID 33511112, 2020). "Among significant obesity genetic risk factors, the common single nucleotide polymorphisms (SNPs) rs9939609 and rs1421085 in the fat mass and obesity-associated (FTO) gene have been consistently reported associated with obesity in distinct populations." (PMID 31915589, 2020). "FTO has been originally reported to contribute to human risk of obesity, mainly through the regulation of food intake." (PMID 31998401, 2020). "For instance, the allele frequency of the FTO-rs12149832 obesity risk alleles differs by 40%, whereas the effect size on BMI is comparable." (PMID 33193685, 2020). "Our study also shows significant associations of FTO SNPs in rs8050136 with the investigated markers of obesity." (PMID 33114268, 2020). "Several studies point to genetic variability amongst obese individuals, specifically in the fat mass and obesity-associated (FTO) gene region of chromosome 16 coding for the FTO protein alpha-ketoglutarate-dependent dioxygenase." (PMID 33304339, 2020). "In contrast to “writers”, “erasers” are proteins that remove specific RNA methylation, also known as demethylases, which include fat mass and obesity-associated (FTO) and ALKBH5." (PMID 32581252, 2020). "The candidate genes were fat mass and obesity-associated (FTO), KCNJ11, potassium voltage-gated channel subfamily Q member 1 (KCNQ1), PDK4, PDX-1, paternally expressed gene-3 (PEG3), PPARG, and stearoyl-coenzyme A desaturase-1 (SCD1)." (PMID 32653024, 2020). "This means that, even though the FTO locus explains most of the interindividual variation in BMI, the ability to predict a person’s obesity risk based only on their FTO genotype is very limited." (PMID 32098227, 2020).